EGF (epidermal growth factor)
Diseases named in the same sentence as EGF in open-access papers (continued):
Sharing a sentence is not in itself a finding about the gene and the disease.
myocardial infarction (4 papers, 2008 to 2025). Gross necrosis of the myocardium, as a result of interruption of the blood supply to the area, as in coronary thrombosis. "Recent evidence shows that these cells contain potent regenerative proteins, such as amphiregulin which can promote tissue repair through epidermal growth factor signalling and have been implicated in myocardial muscle repair post-myocardial infarction as well as wound healing." (PMID 39604770, 2025). "Taken together, these data demonstrate that EGF attenuates oxidative stress and cardiac I/R injury by reducing myocardial infarct size and improving cardiac function possibly via activation of Nrf2." (PMID 34408653, 2021).
Pleural effusion (4 papers, 2013 to 2020). The presence of an excessive amount of fluid in the pleural cavity. "A 75 year-old woman required a minimum pleurotomy (minor surgery) as a consequence of a pleural effusion five months after starting CIMAvax® EGF for NSCLC." (PMID 24127898, 2013). "Similar to the results for pleural effusion of LAC, significantly higher levels of EGF and TGF-β were detected in ACM before and after cultures." (PMID 33235257, 2020).
pterygium (4 papers, 2013 to 2022). A wedge-shaped fibrovascular lesion arising from the bulbar conjunctiva and extending to the cornea. "In addition, GSEA identified the activation of EGF signaling in the 3D pterygium model, underlining the crosstalk between epithelial cells and macrophages." (PMID 35101743, 2022). "Our present research presented that TGF-β and EGF activated the miR-199a-3p/5p-DUSP5/MAP3K11-MAPK axes in the EMT process of pterygium." (PMID 32867783, 2020). "While EGF promotes excessive keratinization and the overexpressed receptor of EGF (EGFR) leaded to increased proliferation in pterygium epithelial cells." (PMID 32867783, 2020). "TGF-β and EGF are overexpressed in pterygium, and it has been reported that both of them can be activated by UVB." (PMID 32867783, 2020). "Our objective was to explore the role of miR-199a-3p/5p in EMT of pterygium based on the established pterygium EMT cell model using HCEs with TGF-β and EGF, and eventually to find new perspectives on treatments for pterygium occurrence and development." (PMID 32867783, 2020). "Epidermal growth factor was also shown to induce cell migration in pterygium epithelium and fibroblasts." (PMID 30515317, 2018). "GSEA revealed that the 3D pterygium model expressed enriched gene hallmarks of TNF-α/NF-κB signaling, EMT, and EGF signaling, while the controls showed enrichment involved in epithelial differentiation and keratinization." (PMID 35101743, 2022). "So, we planned to induce EMT in human conjunctival epithelial cells (HCEs) with TGF-β and EGF, which imitates the EMT initiation in pterygium as a cell model." (PMID 32867783, 2020). "We attempted to establish the pterygium EMT-cell model in HCEs, by using TGF-β and EGF stimulation." (PMID 32867783, 2020). "Furthermore, it presented that miR-199a-3p and miR-199a-5p participated in the process of EMT induced by TGF-β and EGF, by targeting DUSP5 and MAP3K11 in pterygium." (PMID 32867783, 2020). "TGF-β and EGF induce EMT of HCEs through miR-199a-3p/5p-DUSP5/MAP3K11 axes, which explains the pathogenesis of EMT in pterygium and may provide new targets for pterygium prevention and therapy." (PMID 32867783, 2020). "That is to say, TGF-β and EGF affected the expression of DUSP5 and MAP3K11 through regulations on expressions of miR-199a-3p and miR-199a-5p, so as to take part in the MAPK signalling pathway, further to promote the EMT of HCEs, and participate in the initiation and development of pterygium." (PMID 32867783, 2020).
pulmonary arterial hypertension (4 papers, 2012 to 2022). Pulmonary arterial hypertension (PAH) is a group of diseases characterized by mean pulmonary artery pressure >20 mmHg and elevated pulmonary arterial resistance leading to right heart failure. "Because pulmonary hypertension is associated with the overexpression or activation of several RTK receptors, including those for PDGF, FGF2 and EGF, our study aimed to target the majority of these RTK receptors through Suramin treatment." (PMID 24143201, 2013). "Alternatively, growth factors may be important for the maintenance of continued lung growth in patients with pulmonary arterial hypertension, and a favorable phenotype may be associated with increased VEGF and EGF." (PMID 23316102, 2012).
pulmonary TB (4 papers, 2009 to 2023). "Pulmonary TB granulomas, including areas of caseous necrosis, are rich in growth factors such as EGF, TGF-α and VEGF and provide good growth environments for mycobacteria, including M. tb." (PMID 19445695, 2009). "Moreover, it has been demonstrated that EGF combined with the other four tuberculosis specific biomarkers can accurately predict 90.9-100% of active pulmonary tuberculosis." (PMID 36793717, 2023). "EGF, VEGF and TGF-α are growth factors abundant in pulmonary TB granulomas, including areas of caseous necrosis, and provide good growth environments for mycobacteria." (PMID 23691173, 2013).
retinoblastoma (4 papers, 2012 to 2024). A malignant tumor that originates in the nuclear layer of the retina. "We found the SFM maintained an undifferentiated stem cell state and adding bFGF and EGF induced the proliferation of multipotent, self-renewing retinoblastoma stem cells." (PMID 23049239, 2012). "According to currently available data, an increased signal for activators of the MAP-Kinase pathway, such as NGF, epidermal growth factor (EGF), and platelet-derived growth factor (PDGF), was found in pediatric retinoblastoma cell samples." (PMID 39056738, 2024).
serous borderline ovarian tumor (4 papers, 2012 to 2019). "More recently it has been demonstrated that EGF induces serous borderline ovarian tumors cell migration and invasion by activating EMT, which involves the activation of the ERK1/2 and PI3K/Akt pathways and, subsequently, Snail, Slug and ZEB1 expression." (PMID 24816687, 2014). "However, the effect of EGF on serous borderline ovarian tumors (SBOT) and low-grade serous carcinomas (LGC) cell invasion remains unknown." (PMID 22479527, 2012). "ERK signaling also mediates epidermal growth factor-induced SNAIL up-regulation and subsequent cadherin switching and cell invasion in serous borderline ovarian tumor cells." (PMID 27223076, 2016). "Another group found that EGF upregulates Snail1/2 and ZEB1 expression but does not affect Twist in serous borderline ovarian tumor cells (SBOT)." (PMID 31671862, 2019).
steatosis (4 papers, 2021 to 2024). Increased lipid within the cytoplasm of cells. "In a chronic liver injury mouse model recapitulating non-alcoholic fatty liver disease, injections of both HGF and EGF mRNA-LNP sharply reverse steatosis and accelerate restoration of liver function." (PMID 33504774, 2021). "In the more relevant clinical model of NAFLD, HGF and EGF have both been reported to alleviate steatosis, by facilitating release of lipids from hepatocytes to the blood." (PMID 33504774, 2021). "Single injections of either HGF or EGF mRNA-LNP decreased steatosis, although combination of both mRNA-LNP consistently resulted in significantly more efficient steatosis reversion assessed with serum cholesterol levels and Oil Red O staining." (PMID 33504774, 2021). "EGF was significantly increased in patients without steatosis but remained unchanged in patients with steatosis at SVR12." (PMID 39200991, 2024). "Furthermore, EGF was significantly increased in patients without steatosis but remained unchanged in patients with steatosis at SVR12." (PMID 39200991, 2024). "Crucial signaling pathways in HCC pathogenesis include, among others, growth factor signaling via AKT and EGF kinases; however, whether these signaling pathways are influenced by steatosis was not yet known." (PMID 36009822, 2022). "However, a second injection of HGF/EGF mRNA-LNP significantly released cholesterol into the serum, diminished steatosis, and decreased serum ALT levels at T8, suggesting that a repeated regimen of HGF/EGF mRNA-LNP injections could alleviate chronic liver damage." (PMID 33504774, 2021).
tuberculosis (4 papers, 2012 to 2026). A chronic, recurrent infection caused by the bacterium Mycobacterium tuberculosis. "In addition, it has been shown that 10 biomarkers, including CD274 and EGF, can be used for the diagnosis of tuberculosis, the differential diagnosis of latent tuberculosis infection/active tuberculosis, and the risk of progression to active tuberculosis." (PMID 36793717, 2023).
vitamin B12 deficiency (4 papers, 2011 to 2024). A disease characterized by low serum levels of vitamin B12, either inherited or acquired. "This deregulation of the balance between TNF-α and EGF synthesis is induced by cobalamin deficiency." (PMID 21524288, 2011). "Finally, as is common for all drugs, metformin has side effects in some patients causing vitamin B12 deficiency, epidermal growth factor (EGF) reduction, and tumour necrosis factor (TNF) increase." (PMID 39170185, 2024). "Neuropathological lesions in SACD have been found to be due to overproduction of the myelinolytic Tumor necrosis factor α (TNFα) and to the reduced synthesis of the two neurotrophic agents; the Epidermal growth factor (EGF) and interleukin-6 caused by vitamin B12 deficiency." (PMID 26385097, 2015).
ZIKV infection (4 papers, 2018 to 2025). "EGF and IFN-α2 were the two most important inflammatory proteins, with EGF concentration being highest during ZIKV infection and IFN-α2 being highest in CHIKV." (PMID 41346606, 2025). "Correlation of measurements with PC1, which separated ZIKV‐infected patients and healthy controls, showed that a subset of immune mediators (IL‐1RA, EGF, RANTES and IP‐10) and neutrophils were associated with acute ZIKV infection." (PMID 31709049, 2019). "Interestingly, depletion of CD14+ monocytes and ZIKV infection did not affect the levels of epidermal growth factor (EGF), interleukin 9 (IL-9), IL-17A, macrophage inflammatory protein 1α (MIP-1α), and MIP-1β." (PMID 29600283, 2018).
Airway obstruction (3 papers, 2012 to 2015). Obstruction of conducting airways of the lung. "EGF can increase expression of MUC5AC, a mucin associated with airway obstruction in COPD." (PMID 22300528, 2012).
allergic asthma (3 papers, 2020). A asthma with a basis in a pathological type I hypersensitivity reaction. "However, the anti-inflammatory effect on epithelial cells in the lungs related to allergic asthma is the only study in our epidermal growth factor- (EGF-) induced inflammation model." (PMID 32963561, 2020). "In OVA-induced allergic asthma, SOD3 found to interact with epidermal growth factor (EGF) and transforming growth factor (TGF) receptors, adaptors and adhesion molecules, kinases, phosphatases, apoptosis-related factors, and nicotinamide adenine dinucleotide phosphate (NADPH) oxidases." (PMID 32128111, 2020). "Thus, this modulatory action of EGF and FGF21 could be interpreted as harmful, however, it is possible that it is a way to control the large amounts of Th1 and Th2 cytokines that activated NKT can produce, and may contribute, for example, to the development of IgE-mediated allergic asthma." (PMID 32599899, 2020).
Autoimmunity (3 papers, 2012 to 2015). The occurrence of an immune reaction against the organism's own cells or tissues. "In particular, the combination of gastrin hormone and epidermal growth factor (EGF) was among the first combination of compounds that was proposed to stimulate beta cell mass increase or regeneration in beta cell-depleted or autoimmune diabetic mice and has been incorporated in clinical trials." (PMID 26452142, 2015). "The autoimmunity in the LGs of the γDKO mouse was accompanied by an increase in CD4+, CD8+ T- and B-cell infiltration with aging from ages 8 to 16 weeks, an increase in M3R autoantibodies, and a concomitant decrease in EGF concentration in tears." (PMID 23116218, 2012).
autosomal dominant polycystic kidney disease (3 papers, 2019 to 2024). Autosomal dominant form of polycystic kidney disease. "The ratio of urinary epidermal growth factor and monocyte chemotactic peptide 1 is a non-invasive pathophysiological biomarker that can be used for clinical risk stratification in autosomal dominant polycystic kidney disease." (PMID 36342644, 2023).
breast cyst (3 papers, 1989 to 2019). A fluid-filled closed cavity or sac that is lined by an EPITHELIUM and found in the BREAST. "The EGF concentration of 100 ng/ml we used is within the range between 30 and 300 ng/ml that was observed in breast cyst fluids of adult women." (PMID 31532771, 2019). "In the present study, we measured Cath D and Epidermal Growth Factor/alpha Transforming Growth Factor (EGF/alpha-TGF) concentrations in the breast cyst fluid (BCF) of 43 patients with gross cystic disease of the breast." (PMID 1931627, 1991). "In this study we measured the concentrations of epidermal growth factor, dehydroepiandrosterone and its sulphate in breast cyst fluid." (PMID 2528985, 1989).
CADASIL (3 papers, 2022 to 2025). "CADASIL is a progressive disorder with an onset during middle age and is characterised by accumulation of the NOTCH3 Extracellular domain (ECD), which comprises of 34 tandem Epidermal Growth Factor (EGF)-modules." (PMID 40764588, 2025).
cerebral infarction (3 papers, 2017 to 2022). An ischemic condition of the brain, producing a persistent focal neurological deficit in the area of distribution of the cerebral arteries. "Increased expression of epidermal growth factor (EGF) and bFGF after human cerebral infarction probably led to endogenous reparation and it correlated with the proliferation of eNSCs in humans." (PMID 36062152, 2022). "EGFR activated epidermal growth factor, initiated a cascade of downstream signalling events leading to activation of the RAS-RAF-MEK-ERK and PI3K-AKT pathways, and improved the condition of cerebral infarction." (PMID 34434246, 2021).
cervical tumors (3 papers, 2019 to 2024). "Compared with cervical tumors, there is additional EGF in the cervical pre‐tumoroid medium, which promotes the growth of epithelial cells." (PMID 38229169, 2024). "We also examined the EGFR activation upon EGF treatment in cervical tumor-derived cell lines CaSki and HeLa, as before." (PMID 36255238, 2022). "RhoB expression is induced by EGF, PDGF, and many other agents, while several factors including N-Ras and EGFR suppress RhoB promoter activity in NIH3T3 cells and human cancer cell lines derived from lung, pancreatic, and cervical tumors." (PMID 31331053, 2019).
chronic asthma (3 papers, 2006 to 2019). An asthma that is characterized by the development of persistent airway inflammation and recurrent attacks of breathlessness and wheezing, which vary in severity and frequency. "Considering the effect of the ROS scavenger also on EGF-induced proliferation, here we propose that an increase in ROS might be a key component not only of the cysteinyl-LTs enhanced proliferative response, but more generally of the airway remodeling associated with chronic asthma." (PMID 16553950, 2006). "Inhibition of epidermal growth factor (EGF) receptor signalling ameliorated airways hyperreactivity and remodelling in a murine model of chronic asthma." (PMID 25889697, 2015).
chronic hepatitis C (3 papers, 2012 to 2024). "Two articles reporting a relationship between the EGF 61*A/G polymorphism and chronic hepatitis C were also excluded, because the participants in these two articles did not have HCC." (PMID 22403631, 2012).
clear cell renal cell carcinoma (3 papers, 2012 to 2024). "The role of epidermal growth factor (EGF) and its receptor (EGFR) in the pathogenesis and progression of various malignant tumors has long been known, but there is still disagreement concerning prognostic significance of EGFR expression in clear cell renal cell carcinoma (CCRCC)." (PMID 22475688, 2012).
colorectal adenocarcinoma (3 papers, 2013 to 2022). The most common type of colorectal carcinoma. "Here, we report that epidermal growth factor (EGF) increases the expression of claudin-3 in human colorectal adenocarcinoma HT-29 cells." (PMID 24069372, 2013). "Initially, we examined changes in the expression levels of claudin-1 and claudin-3 after EGF treatment in two colorectal adenocarcinoma cell lines, Caco-2 and HT-29, which differ in differentiation status and metastatic potential." (PMID 24069372, 2013). "In the present study, we show that the EGF-mediated increased expression of claudin-3 is related to increased cell migration and the formation of anchorage-dependent and anchorage-independent colonies in human colorectal adenocarcinoma HT-29 cells." (PMID 24069372, 2013). "After checking the capability of KRAS antibody for immunoprecipitation, we examined the cellular interaction of endogenous KRAS and DX2 in colorectal adenocarcinoma DLD-1 cells and observed that the binding of the two proteins was enhanced by EGF treatment." (PMID 35546148, 2022).
colorectal adenoma (3 papers, 2018 to 2025). An adenoma that arises from the colon or rectum. "Studies investigating the role of LGR5 in early colorectal adenomas found that LGR5-KD reduced the survival of epidermal growth factor (EGF)-treated cancer cells, induced proliferation, and enhanced cell cycle progression." (PMID 39821694, 2025). "Our study shows for the first time that EGF exposure represses LGR5 expression in human colorectal adenoma and tumour cells at both the protein and transcriptional level." (PMID 29149105, 2018). "Epidermal growth factor suppresses expression of LGR5 at both the transcript and protein level in colorectal adenoma and carcinoma cells." (PMID 29149105, 2018).
corneal ulcer (3 papers, 2022 to 2025). Area of epithelial tissue loss from corneal surface; associated with inflammatory cells in the cornea and anterior chamber. "Because EGF, which is present in tear film, is known to be safe and effective in reducing the healing time of corneal ulcers, we used an acute alkali burn rat model to compare the corneal healing effects of bleogen pB1 and EGF." (PMID 36052138, 2022). "Thus, since the very beginning, there has been a considerable number of reports on EGF on corneal ulcer healing in animals and humans." (PMID 41471311, 2025). "Previous studies have also demonstrated the importance of EGFR activation for the EGF-mediated corneal epithelial wound healing in various animal models, as well as the potential clinical use of EGF for the management of corneal ulcers in humans." (PMID 36052138, 2022). "With this new conceptual perspective, for corneal ulcer healing, this therapy perspective was now reviewed compared to standard existing eye therapies (i.e., anti-VEGF agents, corticosteroids, EGF, NGF, and others) used in corneal ulcer healing, therapy of neovascularization, and glaucoma therapy." (PMID 41471311, 2025).